PAPLN (papilin, proteoglycan like sulfated glycoprotein)
Synonyms: MGC50452; PPN
Tractability: Antibody: UniProt places it where antibodies can reach, with high confidence; UniProt predicts a signal peptide or a membrane-spanning region; its Gene Ontology location is reachable by antibodies, with medium confidence.
Safety:
Unwanted effects reported when the protein is acted on. In parentheses: how it was acted on, where the effect was seen, and who reports it.
suicidal ideation (source: ClinPGx)
Gene: Protein-coding gene on chromosome 14 (73,236,338 to 73,275,334, forward strand). Ensembl gene ENSG00000100767.
Subcellular location: Secreted
Gene Ontology:
Molecular function: serine-type endopeptidase inhibitor activity
Biological process: extracellular matrix organization
Cellular component: basement membrane; extracellular region
Genetic constraint (gnomAD): Loss-of-function variants: 146 observed, 141.66 expected, observed/expected ratio (o/e) 1.03, 90% interval 0.9 to 1.18. The upper end of that interval is the gene's LOEUF score, 1.18, which puts it in group 5 of 6, group 1 being the genes least tolerant of losing a copy. Missense variants: 1,682 observed, 1,623.4 expected, observed/expected ratio (o/e) 1.04, 90% interval 1 to 1.08. Synonymous variants: 711 observed, 655.97 expected, observed/expected ratio (o/e) 1.08, 90% interval 1.02 to 1.15.
Homologues: Orthologues: chimpanzee PAPLN (99% identical), macaque PAPLN (95% identical), dog PAPLN (79% identical), guinea pig PAPLN (75% identical), mouse Papln (74% identical), rat Papln (73% identical), rabbit PAPLN (73% identical), pig PAPLN (57% identical), tropical clawed frog papln (45% identical), zebrafish paplna (30% identical), zebrafish paplnb (18% identical). Paralogues in human: THSD4 (20% identical), ADAMTSL4 (20% identical), ADAMTS7 (19% identical), ADAMTS9 (19% identical), ADAMTS12 (18% identical), ADAMTS18 (18% identical), ADAMTS16 (18% identical), ADAMTS20 (18% identical), ADAMTSL2 (16% identical), ADAMTS6 (16% identical), ADAMTSL1 (16% identical), ADAMTS13 (16% identical), and 13 more.
Diseases named in the same sentence as PAPLN in open-access papers:
PAPLN is named in the same sentence as 5 diseases in open-access papers, as found by Europe PMC text mining. Sharing a sentence is not in itself a finding about the gene and the disease. The quoted sentences say what the papers report.
liver diseases (1 paper, 2021). "The PAPLN is a component of the extracellular matrix, widely studied in humans, and it has been related to liver diseases and growth." (PMID 34773987, 2021).
cancer (1 paper, 2023). A tumor composed of atypical neoplastic, often pleomorphic cells that invade other tissues. "Little research has been conducted on the link between PAPLN and cancer." (PMID 37214471, 2023).
PAPLN also shares sentences with these, for which no sentence is quoted: hyperprolactinemia (1 paper); lobular carcinoma (1); tumor (1).